PRRT3 (proline rich transmembrane protein 3)
Synonyms: FLJ33674
Tractability: Antibody: UniProt predicts a signal peptide or a membrane-spanning region; the Human Protein Atlas places it where antibodies can reach.
Gene: Protein-coding gene on chromosome 3 (9,939,450 to 9,952,424, reverse strand). Ensembl gene ENSG00000163704.
Subcellular location: Membrane
Subcellular location (Human Protein Atlas): Plasma membrane; Nucleoplasm
Gene Ontology:
Cellular component: membrane
Genetic constraint (gnomAD): Loss-of-function variants: 51 observed, 47.29 expected, observed/expected ratio (o/e) 1.08, 90% interval 0.86 to 1.36. The synonymous counts are far from expectation, so gnomAD's model fits this gene poorly and the ratio says little. Missense variants: 1,335 observed, 1,141.2 expected, observed/expected ratio (o/e) 1.17, 90% interval 1.12 to 1.22. Synonymous variants: 627 observed, 515.74 expected, observed/expected ratio (o/e) 1.22, 90% interval 1.14 to 1.3.
Homologues: Orthologues: chimpanzee PRRT3 (99% identical), macaque PRRT3 (95% identical), pig PRRT3 (81% identical), dog PRRT3 (80% identical), rabbit PRRT3 (77% identical), rat Prrt3 (75% identical), mouse Prrt3 (73% identical), guinea pig PRRT3 (69% identical), zebrafish si:ch211-14i3.2 (17% identical). Paralogues in human: PERM1 (11% identical).
Diseases named in the same sentence as PRRT3 in open-access papers:
PRRT3 is named in the same sentence as 6 diseases in open-access papers, as found by Europe PMC text mining. Sharing a sentence is not in itself a finding about the gene and the disease. The quoted sentences say what the papers report.
cancer (1 paper, 2023). A tumor composed of atypical neoplastic, often pleomorphic cells that invade other tissues. "MPL (proto-oncogene), NAV1 and PRRT3 are putative oncogenes implicated as candidate cancer drivers." (PMID 37166351, 2023).
tumor (1 paper, 2020). "Two down-regulated tumor-property-specific lncRNAs (XLOC_010739, G015949) was found to be correlated with 4 down-regulated genes (PRRT3, AL590560.1, AC114783.1 and AZGP1) (boxed in orange)." (PMID 32636408, 2020).
PRRT3 also shares sentences with these, for which no sentence is quoted: dermatitis (1 paper); HIV-1 infection (1); pheochromocytoma (1); retinal angiomas (1).